INS (insulin)
Diseases named in the same sentence as INS in open-access papers (continued):
Sharing a sentence is not in itself a finding about the gene and the disease.
diabetes (continued). "Other risk factors identified were: advanced age, black skin color, longer length of diabetes diagnosis, daytime sleepiness, macroalbuminuria, genetic polymorphisms, insulin therapy, use of oral antidiabetics, and use of metoclopramide, inadequate physical activity and low fasting glycemia." (PMID 28591300, 2017). "In patients with diabetes, the secretory response of α cells to low-glucose concentrations is impaired predisposing to risk of hypoglycaemia, especially in patients treated with insulin." (PMID 28634585, 2017). "Diabetes mellitus (DM), a major epidemic of this century, is a metabolic syndrome characterized as high blood sugar, which is caused by disorder of insulin secretion or functioning." (PMID 28798909, 2017). "A number of dysregulated miRNAs from insulin-sensitive organs, including skeletal muscle, white adipose tissue and insulin-producing pancreatic β-cells, has been linked to processes related to diabetes, such as insulin secretion, pancreatic β-cells and adipocyte differentiation." (PMID 28264477, 2017). "One hundred and forty one respondents (35.25%) agreed that a lack or defect of insulin may cause diabetes, among the respondents who agreed with the statement more were female (37.61%) than male (31.93%)." (PMID 28970423, 2017). "In addition, a most-recent published systematic review and meta-analysis of randomized clinical trials reported that oral Mg supplementation improved insulin-sensitivity parameters in those who were at high risk for diabetes." (PMID 28927411, 2017). "Some authors have also indicated a correlation between butyrylcholinesterase (BuChE) and insulin sensitivity, which implies that BuChE could have a crucial role in diabetes associated with insulin resistance." (PMID 28770024, 2017). "More precise method for measuring insulin secretion, such as clamp studies, could elucidate better the mechanism of role of insulin action on the association between Lp(a) level and diabetes development." (PMID 28510610, 2017). "Alternatively, diabetes may be linked to reduced β-cell proliferation with abnormal insulin trafficking and secretion, as observed in EIF2AK3 knockout mice." (PMID 28049534, 2017). "Several authors have reported that the relationship between diabetes and cognitive impairment may be associated with lowered insulin levels and its resistance." (PMID 28770024, 2017). "Type 1 diabetes mellitus (T1D) is an autoimmune-mediated disease in which pancreatic beta cells are destroyed by the immune system, thus causing life-long dependence on exogenous insulin therapy." (PMID 29096722, 2017). "This causes a large reduction in the production of insulin, which results in diabetes." (PMID 27598977, 2017). "Furthermore, since obesity constitutes a strong risk factor for diabetes, the associated low vitamin D levels, decreased insulin secretion, and or decreased insulin sensitivity contribute to the complexity of the effect of obesity on bone health." (PMID 28124221, 2017). "Such excess risk cannot be due to insulin or OHAs, rather, it might be confounded or mediated by overweight and obesity, which are well- known risk factors for both diabetes and many type of cancers." (PMID 29070034, 2017). "Furthermore, it is known to exert anti–type 2 diabetes mellitus (T2D) effects associated with improvements of dyslipidemia and insulin secretion, as well as decreased insulin resistance in T2D." (PMID 28938451, 2017). "Hence, insulin sensitizers are one class of drugs currently employed to treat diabetes and associated metabolic disorders." (PMID 29023424, 2017). "Prescribing errors at the time of hospital discharge are common and could potentially lead to avoidable patient harm, especially when they involve insulin, a high-risk medicine widely used for the treatment of diabetes mellitus." (PMID 28852529, 2017).
diabetes (continued). "All models were adjusted for duration of diabetes, total cholesterol level, use of insulin, use of anti-hypertensive drugs as significant risk factors in univariate analysis and for age, sex, fasting C-peptide level and smoking status as known associated factors of CAN (Model 1–3)." (PMID 29017498, 2017). "In addition, low endogenous insulin secretion was also associated with muscle mass among patients with diabetes." (PMID 28246927, 2017). "We began the analysis by aiming on insulin-signaling and associated cellular genes, a natural and well-established candidates for finding a signature set of genes associated with insulin resistance or diabetes." (PMID 28179884, 2017). "The remaining effect of serum magnesium levels on diabetes and prediabetes risk could occur via insulin secretion or through its impact on insulin signalling." (PMID 28224192, 2017). "However, since the discovery of the therapeutic application of insulin in the 1920s, diabetes mellitus has become a chronic disease that causes many complications, including retinopathy, nephropathy, vasculopathy and neuropathy." (PMID 28492724, 2017). "Diabetes mellitus is a disorder characterized with persistent hyperglycemia in the blood resulting from either deficiency in insulin secretion from pancreatic β cells and/or resistance to insulin." (PMID 29023424, 2017). "Normal HbA1C values confirm the exclusion of diabetes in our insulin-resistant participants who are at risk for T2D but in whom elevated insulin release may still compensate for reduced insulin sensitivity." (PMID 28719580, 2017). "Similarly, MODY (Maturity Onset Diabetes of the Young) represent a distinct group of diabetic disorders characterized by the impairment of pancreatic β-cells (the insulin-producing cells) caused by an autosomal dominantly inherited mutations." (PMID 28684784, 2017). "Thus, systemic administration of miR-106b and miR-222 mimics promotes post-injury β-cell regeneration, thereby ameliorating insulin-deficient diabetes." (PMID 27974246, 2017). "Diabetes mellitus are described as a complex and serious condition of metabolic disease associated with abnormally high levels of blood sugar (glucose) resulting from deficiency of insulin secretion and/or action." (PMID 29295509, 2017). "The mechanism for developing diabetes mellitus is unclear but may relate to a radiation-induced effect on the pancreas, perhaps causing inflammation and fibrosis, which may reduce subsequent insulin secretion from the islet cells." (PMID 28419299, 2017). "It is unknown whether maintaining lower SF levels in persons with HFE hemochromatosis and diabetes than presently recommended for “maintenance” therapy could maintain or improve insulin secretion and diabetes control or decrease diabetes risk." (PMID 28331855, 2017). "Furthermore, intravenous administration of the corresponding miRNA mimics promoted post-injury β-cell proliferation, thereby ameliorating hyperglycemia of insulin-deficient diabetes." (PMID 27974246, 2017). "Increased β-cell function and insulin sensitivity may contribute to the reduced risk for diabetes in individuals who returned to normoglycemia during the intervention." (PMID 28168204, 2017). "It has also been reported that excess alcohol may reduce insulin-mediated glucose uptake and can cause injury to pancreatic islet β-cells resulting in type 2 diabetes mellitus." (PMID 29113391, 2017). "Third, the finding that insulin resistance contributes more to diabetes risk in subjects with low Lp(a) level may be due to the use of fasting measures to determine insulin secretion in this study." (PMID 28510610, 2017). "Furthermore, eight of the 17 CpG sites reside in genes (FSTL1, SORCS2, NRF1, DLC1, PPARGC1B, CHN2, NXPH1) that have prior known associations with obesity, diabetes, and the insulin pathway." (PMID 28068899, 2017).
diabetes (continued). "In the multivariate model, which includes the duration of diabetes and BMI in addition to age and gender as covariates (multivariate model 1), the patients with treated with insulin were at a significantly lower risk for the decline of SMI than those who did not receive insulin treatment." (PMID 28246927, 2017). "While there is accumulating evidence to suggest that rs13266634 impacts diabetes risk and insulin secretion traits and is affected by total zinc intake and circulating zinc levels, the functional implications of the rs13266634 variant remain unclear." (PMID 29093761, 2017). "Diabetes mellitus is a chronically metabolic disorder with abnormally high levels of blood glucose (hyperglycemia), which is caused by the deficiency in insulin secretion and/or the decreased response of the organs to insulin." (PMID 29344419, 2017). "While there is evidence that a loss of insulin signalling to podocytes is detrimental, the molecular mechanisms underpinning the development of podocyte insulin resistance in diabetes remain unclear." (PMID 28852804, 2017). "Interestingly, prospective population-based studies have shown that low natriuretic peptides levels are associated with an increased risk of diabetes incidence and an inverse relationship between natriuretic peptide and insulin sensitivity has also been found." (PMID 28946871, 2017). "Furthermore, the urban subjects had higher body mass index (BMI), waist circumference, and insulin levels, consistent with studies showing an association between urbanization, obesity, and diabetes." (PMID 28915922, 2017). "The associations between diabetes and tumor subtypes among type 1 diabetes insulin users were more in line with the findings in the non-insulin users (e.g. poor prognosis tumors), while we observed a suggestion that type 2 diabetes insulin users had better prognosis tumors." (PMID 28076434, 2017). "Furthermore, in studies with streptozotocin-induced diabetes in rats, disturbance of insulin signaling was associated with low levels of hepcidin, whereas insulin treatment reversed these changes." (PMID 28841871, 2017). "However, Fh1βKO mice subsequently developed rapidly progressing diabetes, culminating in severe glucose intolerance, reduced islet insulin content, and almost complete loss of GSIS." (PMID 28954230, 2017). "We conducted a matched case-control analysis using data from the U.K.-based Clinical Practice Research Datalink (CPRD) to analyse diabetes status, duration of diabetes, glycemic control, and use of metformin, sulfonylureas, and insulin in relation to the risk of meningioma." (PMID 28708856, 2017). "Therefore, further large-scale longitudinal observational studies are needed to elucidate the association between the use of insulin in patients with diabetes and gastric malignancy." (PMID 29082856, 2017). "But, it is uncertain whether epigenetics is associated with diabetes medication, such as metformin or insulin." (PMID 28947922, 2017). "We examined the DNA methylation of these genes in the liver of subjects with type 2 diabetes and tested whether epigenetic alterations associate with diabetes medication, i.e., metformin or insulin plus metformin treatment." (PMID 28947922, 2017). "Taken together, a large body of evidence suggests that Abcg1 could play a role in diabetes as well as in accelerated atherosclerosis associated to diabetes through modulation of insulin secretion and foam cell formation, respectively." (PMID 28869506, 2017). "Recently, melatonin could improve the impaired memory caused by diabetes at 10 mg/kg in rats by improving neurogenesis, synaptogenesis in hippocampi, increasing the receptors of melatonin and insulin, and restoring the downstream signaling pathway for insulin." (PMID 28387721, 2017). "Type 1 diabetes mellitus is resulting from autoimmune destruction of the β-cells of the pancreas with consequent insulin deficiency to abnormalities that result in resistance to insulin action." (PMID 29295509, 2017).
diabetes (continued). "The results indicate that the intake of dairy products, specifically whey proteins, may be associated with glucose-insulin homeostasis in individuals with SNPs related to the risk of diabetes." (PMID 28867816, 2017). "Interestingly, diabetes treated with insulin has been linked to increased 30-day readmission rates for people undergoing arthroplasty." (PMID 28265893, 2017). "Atherogenic dyslipidaemia, in particular elevated triglycerides, a marker for increased triglyceride-rich lipoproteins and their remnants, is an important contributor to lipid-related residual risk, especially in insulin resistant conditions such as type 2 diabetes mellitus." (PMID 28978316, 2017). "Better insulin sensitivity leads directly to a decreased risk of diabetes, so these results may be because of differences in how the participants lost or gained weight (ie, whether they lost or gained fat or muscle mass)." (PMID 28596244, 2017). "Thus, ZB-16 rescues the stimulated insulin and incretin secretion in animals with type 2 diabetes mellitus caused by streptozotocin and nicotinamide administration." (PMID 28736546, 2017). "Furthermore, intravenous administration of the corresponding miRNA mimics promoted post-injury β-cell proliferation through Cip/Kip family down-regulation, thereby ameliorating hyperglycemia in mice with insulin-deficient diabetes." (PMID 27974246, 2017). "More information is certainly needed about the associations between statin use, glycaemic control and CV risk specifically in the insulin-treated T2D population, because these patients tend to have more complications, higher absolute CV risk and a longer duration of diabetes." (PMID 28830436, 2017). "Decreased insulin secretion increases diabetes risk in persons with hemochromatosis." (PMID 28331855, 2017). "Interestingly, only the mutation of insulin and chromogranin resulted in protection against diabetes." (PMID 29312143, 2017). "Metformin is known as an insulin sensitizer and has been demonstrated to prevent the development of diabetes, promote weight loss, and reduce the incidence of metabolic syndrome, which may lead to a more favorable cardiovascular risk profile." (PMID 29065479, 2017). "Since numerous studies have concluded that patients with diabetes have an increased risk of developing Alzheimer's disease (AD) compared to healthy individuals, the interaction between insulin signaling and the CNS has received significant attention in the last decade." (PMID 28584820, 2017). "This may be proof that maternal intake of added sugar might alter the development of glucose and insulin regulation pathways, β cell function of the fetus, and may cause predisposition to diabetes." (PMID 29191195, 2017). "Furthermore, intravenously administered miR-106b/222 promoted β-cell proliferation, thereby ameliorating hyperglycemia in mice with insulin-deficient diabetes." (PMID 27974246, 2017). "We suspect that diabetic patients with lower C-peptide serum levels and lower levels of endogenous insulin secretion might suffer from much more beta-cell failure due to the longer duration of illness associated with diabetes." (PMID 28455662, 2017). "Similarly, increased site-specific cancer risks among individuals with type 1 and 2 diabetes, though showing a smaller excess risk for type 1 diabetes, suggest that a common diabetes-related determinant other than insulin use affects the cancer incidence." (PMID 28573394, 2017). "Type 1 Diabetes Mellitus (T1DM) is a metabolic disorder characterized by hyperglycemia caused by autoimmune-mediated destruction of pancreatic β cells leading to a complete or near total loss of the hormone insulin." (PMID 28813430, 2017). "However, the precise mechanisms by which leptin controls cardiovascular function in insulin-deficient diabetes and how leptin is capable of completely normalizing glucose levels even in the absence of adequate insulin production are still unclear." (PMID 29190687, 2017).
diabetes (continued). "Type 1 diabetes mellitus is characterised by the immune-mediated destruction of pancreatic beta cells leading, ultimately, to the loss of insulin production and lifelong dependence on exogenous insulin." (PMID 27796422, 2017). "Insulin was the marker most strongly associated with self-reported diabetes." (PMID 28753646, 2017). "According to this hypothesis, leaner people with longer diabetes duration are not only more insulin-deficient, but also remain more insulin-deficient at mealtime after supplementation of basal insulin, as compared with patients with BMI ≥30." (PMID 28151905, 2017). "Double diabetes tends to occur when the pro-inflammatory state associated with metabolic syndrome leads to reduced glycemic control, eventually requiring higher daily doses of insulin [18•]." (PMID 28836234, 2017). "Insulin therapy and diabetes duration are related to a higher risk of severe hypoglycaemia and might confound the association between factors included in the analysis, such as age and comorbidities, and risk of readmission." (PMID 28314943, 2017). "By not having induced insulin resistance through high-fat diet, this animal model allowed the evaluation of the impact of chronic hyperglycemia (induced by insulin reduction) on bone quality and excluded in part the crosstalk of other complex metabolic factors linked to diabetes condition." (PMID 29081798, 2017). "However, as insulin signaling is essential for glucose homeostasis, this decreased insulin signaling should cause diabetes mellitus." (PMID 28367331, 2017). "Graphical abstract: Early circadian IR disorders caused by overweight and obesity are associated with increased risk for diabetes via formation of a vicious cycle between lipid anabolic and catabolic programs thus distorting insulin and lipid levels in day/night period." (PMID 28884000, 2017). "Diabetes mellitus comprises a group of metabolic diseases in which the characteristic phenotype is loss of control of glucose homeostasis, resulting from defects in insulin secretion, insulin action or both." (PMID 28303212, 2017). "A more severe decline in beta cell function may cause a quicker switch from oral anti-diabetes drugs to insulin injections in early-onset diabetes participants." (PMID 28422176, 2017). "Several studies have investigated whether diabetes and/or insulin (analogue) treatment increase breast cancer risk or affect prognosis, because of their potential impact on tumor progression through e.g. the insulin-like growth receptor pathway." (PMID 28076434, 2017). "Investigating central insulin action might therefore be confounded by impaired transport of the hormone into the brain in individuals at risk for diabetes." (PMID 28719580, 2017). "Therefore, the objective of this study was to assess the pattern of adherence to insulin self administration and associated factors among adult patients with diabetes mellitus at endocrinology unit of Tikur Anbessa Specialized Hospital Addis Ababa Ethiopia." (PMID 28680863, 2017). "In reality, the affordability of insulin may be even worse because diabetes is associated with poverty and many diabetic patients earn a lower wage than the lowest paid unskilled government workers." (PMID 28836974, 2017). "The incoherent insulin pulses at prolonged hyperglycemia may suggest another reasoning for the loss of insulin pulsatility under diabetes, in addition to the deteriorated pulse generation of individual islets." (PMID 28235104, 2017). "EDS, defined in our study as daytime sleep of >1 h, is associated with many adverse characteristics such as obesity, physical inactivity, diabetes, breathlessness, use of antihypertensive therapy and with an adverse pattern of metabolic risk factors including HbA1c, glucose and insulin." (PMID 28674146, 2017).